LEF1 (lymphoid enhancer binding factor 1)
Diseases named in the same sentence as LEF1 in open-access papers (continued):
Sharing a sentence is not in itself a finding about the gene and the disease.
hypohidrotic ectodermal dysplasia (1 paper, 2022). A genetic disorder of ectoderm development characterized by malformation of ectodermal structures such as skin, hair, teeth and sweat glands. "Recently, de novo microdeletions encompassing the LEF1 gene have also been identified in two unrelated patients with severe oligodontia and other features compatible with hypohidrotic ectodermal dysplasia." (PMID 36294409, 2022).
hypospadias (1 paper, 2024). Hypospadias is the displacement of the urethral meatus on the ventrum of the penis. "We utilized RT‐PCR and Western blot techniques to investigate the Wnt signaling pathway and observed a significant reduction in both mRNA and protein levels of SOX9, Wnt3a, LEF1, GSK3β, NF‐κB, TCF1, and cyclin D1 in the samples of hypospadias." (PMID 40626133, 2024).
Infertility (1 paper, 2023). "Unfortunately, infertility of Ptendel; Fbxw7mut females (owing to the rapid onset of endometrial neoplasia) precluded breeding to generate GEMM with concomitant Lef1 deletion, meaning that we were unable to examine whether the tumour phenotype was rescued by Lef1 loss." (PMID 37589076, 2023).
intestinal cancer (1 paper, 2021). "We show that deletion of Lef1 in three different Apc-mutant intestinal cancer models accelerates tumor initiation and growth and concomitantly increases the expression of the Wnt-downstream targets Myc and Cd44." (PMID 34788095, 2021).
intracranial hemorrhage (1 paper, 2025). Bleeding within the SKULL, including hemorrhages in the brain and the three membranes of MENINGES. "Therefore, LEF1, BLVRB, ITGAX and ATF4 are expected to become new biomarkers for intracranial hemorrhage." (PMID 40933575, 2025).
kidney cancer (1 paper, 2019). Primary or metastatic malignant neoplasm involving the kidney. "LEF1 levels correlated with poor prognosis of various solid tumors including lung and kidney cancers." (PMID 31623618, 2019).
laryngeal carcinoma (1 paper, 2017). Carcinoma that arises from the laryngeal epithelium. "miR-27 asignificantly rescued differentiation and inhibited β-catenin, LEF1, OCT4 and SOX2 in Wnt/β-catenin pathway in all-trans-retinoic acid (ATRA)-induced laryngeal cancer cells." (PMID 28122350, 2017).
laryngeal squamous cell carcinoma (1 paper, 2022). A squamous cell carcinoma that arises from the larynx. "FOXP4 directly acts on LEF-1 and gives impetus to the occurrence of laryngeal squamous cell carcinoma." (PMID 36160018, 2022).
latent infection (1 paper, 2023). "The EBV-infected NOK showed resistance to differentiation and a LEF1-dependent increase in cellular invasiveness suggesting that EBV latent infection reprogrammed cells with a basal cell, wound-healing cellular phenotype." (PMID 38113273, 2023).
Listeria monocytogenes infection (1 paper, 2013). "Zhou and Xue made an effort in this direction when they studied the effect of double deficiency of TCF-1 and LEF-1 on generation of memory precursors in effector CD8 T cell populations in response to Listeria monocytogenes infection." (PMID 24171157, 2013).
liver disease (1 paper, 2013). "We found significant fold changes for SPINK1, LEF1, TSPAN8, SPP1, OR2I1P and PTGFRN comparing HH-HCC with HH-liver disease and normal liver (p<0.05, one-way Anova)." (PMID 23527199, 2013).
liver fibrosis (1 paper, 2019). "Lymphoid enhancer binding factor Lef1 is essential for the early stages of thymocyte maturation, and is involved in liver fibrosis." (PMID 31269941, 2019).
lung diseases (1 paper, 2015). "TCF7 interacts with multiple proteins and target genes (e.g. CD3E, β-catenin, TCF7L2, LEF-1, IL-17, IL-4, or Eomes) and is involved in several signal pathways (e.g. Wnt, FoxO1, Notch, or P21pathways) which are critical for lung diseases, especially the canonical Wnt/β-catenin pathway." (PMID 26289446, 2015).
lymph node enlargement (1 paper, 2015). "The patients with LEF1 high expression were also significantly higher for the presence of splenomegaly and lymph node enlargement compared to those with LEF1 low expression (68.4% vs 29.4%, P = 0.003; 63.2% vs 28.3%, P = 0.007)." (PMID 25942645, 2015).
marginal zone lymphoma (1 paper, 2025). A usually indolent mature B-cell lymphoma, arising from the marginal zone of lymphoid tissues. "In this case, despite CD23 negativity, CD43, CD200, and LEF1 positivity support the diagnosis of CLL/SLL, whereas cyclin D1 and SOX11 negativity and LEF1 positivity exclude mantle cell and marginal zone lymphoma, respectively." (PMID 40893576, 2025).
metastatic tumors (1 paper, 2021). "Higher level of TAP1 in metastatic tumors were associated with higher levels of vimentin and LEF1, while associated with lower level of E-cadherin." (PMID 34957213, 2021).
Nephropathy (1 paper, 2016). A nonspecific term referring to disease or damage of the kidneys. "However, it did not significantly reduce the increased expression of fibronectin, further increased the expression of LEF1, upregulated PAI-1 (CD2AP−/−+tankyrase inhibitor), a fibrogenic factor that has been associated with the development of nephropathy, and increased pro-apoptotic signaling." (PMID 27441654, 2016).
ovarian adenocarcinoma (1 paper, 2003). An adenocarcinoma that arises from the ovary. "Adenomatous polyposis coli expression was decreased or absent in ovarian adenocarcinomas, while Lef-1 was constantly expressed in all the tissues analysed." (PMID 14520463, 2003).
ovarian serous adenocarcinoma (1 paper, 2003). An adenocarcinoma that arises from the ovary and is characterized by the presence of malignant epithelial cells that, in well differentiated tumors, resemble the epithelium of the fallopian tube or, in poorly differentiated tumors, show anaplastic features and marked nuclear atypia. "This could explain why Lef-1, in our study, was found to co-precipitate with β-catenin in an ovarian serous adenocarcinoma and in the OVCAR-3 cell line." (PMID 14520463, 2003).
ovarian tumours (1 paper, 2003). "The immunoprecipitation with Lef-1 in the ovarian tumour sample also contained a band for β-catenin at the expected size of 92 kDa (lane 3)." (PMID 14520463, 2003). "Nuclear localisation of β-catenin or Lef-1 could not be demonstrated in the normal ovary or in the ovarian tumours." (PMID 14520463, 2003). "Beta-catenin and Lef-1 were coimmunoprecipitated in ovarian tumours, but not in the normal ovary." (PMID 14520463, 2003). "Nuclear staining for β-catenin and Lef-1, indicating dysfunction in normal Wnt-signalling, was found in the OVCAR-3 cells but not in ovarian tumour biopsies." (PMID 14520463, 2003).
pancreatic ductal adenocarcinoma (1 paper, 2020). An infiltrating adenocarcinoma that arises from the epithelial cells of the pancreas. "LEF1 and AR were also expressed in majority of SPNs, while pancreatic ductal adenocarcinomas and pan NETs showed no expression." (PMID 33298094, 2020).
pancreatic neuroendocrine tumor (1 paper, 2025). Pancreatic endocrine tumor, also known as pancreatic neuroendocrine tumor (PNET), describes a group of endocrine tumors originating in the pancreas that are usually indolent and benign, but may have the potential to be malignant. "LEF1 expression in pancreatic neuroendocrine tumors is almost always negative; however, occasionally, patient with positive expression have been reported." (PMID 39881334, 2025).
Pancreatoblastoma (1 paper, 2025). A rare malignant epithelial neoplasm arising from the pancreas. "LEF1 expression in pancreatoblastomas is mainly confined to squamoid corpuscles." (PMID 39881334, 2025).
rectal cancer (1 paper, 2021). A primary or metastatic malignant neoplasm that affects the rectum. "Immunohistochemistry was used to detect the protein expression of LEF1 and CyclinD1 in LRRC, primary rectal cancer (PRC), and non-recurrent rectal cancer (NRRC) specimens." (PMID 34642262, 2021).
retinopathy of prematurity (1 paper, 2017). A bilateral retinopathy characterized by neovascularization, scarring, retinal detachment, and eventually blindness. "Levels of THBS1, MMP8, MMP9, MMP25, TIMP2 and TIMP3 increased as severity of BPD and retinopathy of prematurity (ROP) increased, whereas ETS1, LEF1 and SPOCK2 exhibited the opposite trend." (PMID 28103583, 2017).
rheumatoid arthritis (1 paper, 2024). A chronic, systemic autoimmune disorder characterized by inflammation in the synovial membranes and articular surfaces. "In rheumatoid arthritis, MAGMA across five ancestry groups identified 34 novel loci, and multiancestry fine‐mapping identified a putative causal variant at the LEF1 locus, which is of interest as LEF1 has a role in CD4+ T cells, which are relevant to rheumatoid arthritis biology." (PMID 39022911, 2024).
salivary gland tumors (1 paper, 2025). "LEF1 is expressed in other salivary gland tumors, but its expression in BA is significantly higher." (PMID 39881334, 2025).
Sepsis (1 paper, 2023). Sepsis is defined as life-threatening organ dysfunction caused by a dysregulated host response to infection. "Therefore, LEF1, as a hub gene, may play a crucial role during sepsis and may predict the outcome of septic patients." (PMID 37091800, 2023). "In the study, we found that 4 necroptosis-related hub genes (BACH2, GATA3, LEF1, and BCL2) were closely related to sepsis, providing a potential new target for the diagnosis and therapy of sepsis." (PMID 37091800, 2023). "In the present study, we identified 47 DE-NRGs between sepsis and healthy control in the dataset GSE65682 and screened out 4 hub genes (BACH2, GATA3, LEF1, and BCL2) via various machine learning algorithms." (PMID 37091800, 2023). "In conclusion, using machine learning analysis we identified 4 necroptosis-related hub genes (BACH2, GATA3, LEF1, and BCL2), which could be used as the potential di-agnostic and prognostic biological marker in sepsis." (PMID 37091800, 2023).
serous adenocarcinoma (1 paper, 2003). An adenocarcinoma that is characterized by the presence of papillary patterns and cellular budding. "A serous adenocarcinoma was immunoprecipitated with β-catenin, Lef-1, Tcf/Lef, α-catenin or Axin and blotted for the detection of α-catenin, β-catenin or Lef-1." (PMID 14520463, 2003).
Solid Pseudopapillary Neoplasm of the Pancreas (1 paper, 2021). A low-grade malignant neoplasm that arises from the exocrine pancreas. "LEF1 IHC has been recently introduced as a useful tool in the diagnosis of solid-pseudopapillary neoplasm of the pancreas, a tumour with a gain-of-function mutation in CTNNB1." (PMID 34420090, 2021).
synovitis (1 paper, 2022). Inflammation of a synovial membrane. "Using a posttraumatic OA model (PTOA), we find that cartilage-specific Sirt1 genetic nulls caused severe synovitis and mineralization of the lateral joint compartment, due to augmented Lef1 gene expression." (PMID 35594394, 2022).
thymic lymphoma (1 paper, 2012). "Thus, in the absence of normal regulatory mechanisms in thymic lymphoma cells provided by E2A or Tcf1, Lef1 can act as an important oncogene." (PMID 23185135, 2012).
thyroid carcinomas (1 paper, 2020). "LEF-1 has also been suggested as a sensitive biomarker for cribriform-morular thyroid carcinomas in a recent series; however, the global experience is largely lacking with respect to LEF-1 expression in these neoplasms." (PMID 32632840, 2020).
type A thymoma (1 paper, 2020). "The upstream regulator analysis showed these differential proteins with their overexpression in type A thymoma were likely regulated by HBEGF, LEF1, and GLIPR1." (PMID 31967407, 2020).
vitiligo (1 paper, 2024). Generalized well circumscribed patches of leukoderma that are generally distributed over symmetric body locations and is due to autoimmune destruction of melanocytes. "It was found that the expression of Wnt pathway components such as LEF1, CDH2, and CDH3 was downregulated in the lesional skin of vitiligo." (PMID 38361944, 2024). "In addition, it was found that the expression of Wnt pathway components such as LEF1, CDH2, and CDH3 was downregulated in the lesional skin of vitiligo." (PMID 38361944, 2024).
tumor (236 papers, 2003 to 2026). "In nude mouse transplanted tumors, overexpression of LEF1 reverses the tumor growth inhibition caused by NCAPG knockdown." (PMID 39744480, 2025). "The diagnostic rate of LEF1 alone, β-catenin alone, and their combination were compared for each tumor type and all patients." (PMID 39881334, 2025). "As an effector of the Wnt signalling pathway, LEF1 is also associated with regulating the cell cycle, epithelial-to-mesenchymal transition, and with tumour development and progression." (PMID 38792023, 2024). "Here we show, in a murine model of T-ALL arising due to E2a inactivation, that the developmental timing of Lef1 mutation impacts its ability to function as a cooperative tumor suppressor or oncogene." (PMID 35371057, 2022). "Collaboration with LEF1 to activate TGFβR2 gene transcription is a vital mechanism underlying the tumour-promoting capacities of Pontin." (PMID 36153326, 2022). "Tumours with both nuclear beta-catenin and nuclear LEF1 protein expression were significantly associated with CTNNB1 mutation." (PMID 34420090, 2021). "IHC showing nuclear beta-catenin and LEF1 overexpression are associated with CTNNB1 exon 3 mutation in these tumours, having nuclear beta-catenin a better specificity for CTNNB1 mutation." (PMID 34420090, 2021). "As expected, tumours harbouring CTNNB1 exon 3 mutation showed a higher LEF1 Allred score in accordance with proteomic data from CPTAC study." (PMID 34420090, 2021). "Nuclear beta-catenin shows a higher positive predictive value than LEF1 for CTNNB1 exon 3 mutation in these tumours." (PMID 34420090, 2021). "Tumor burden in Lef1- and Cbx3-Lef1-deficient animals was higher than that observed for Cbx3/HP1γ-deficient and control mice." (PMID 34721405, 2021). "The abnormal Wnt/β-catenin signaling pathway activation with increased TCF4 and LEF1 levels is also implicated in tumorigenesis and tumor progression in various cancer types." (PMID 32933177, 2020). "Several studies indicated that LEF1 was overexpressed in lung adenocarcinomas and oral squamous cell carcinoma, and its aberrant expression was closely associated with tumor progression and poor prognosis." (PMID 31296250, 2019). "Conversely, the downregulation of LEF1 significantly decreased tumor growth and tumorigenicity and caused a decrease in OV6 and LEF1 expression levels compared with the vector control." (PMID 31296250, 2019). "The different members of the Lef/Tcf transcription factor family have been implicated in tumorigenesis, and we found strong upregulation of Tcf1 and Lef1 in the tumor models, which were only in part downregulated by Pygo2 loss." (PMID 27811361, 2016). "If E-cadherin is lost, β-catenin is not retained in the plasma membrane and can be then translocated into the nucleus, thus activating Tcf/Lef-1 transcription factors-mediated expression of genes implicated in cell proliferation and tumor progression." (PMID 18694510, 2008). "LEF1, though slightly lower-ranked in consensus scoring, is a well-established transcription factor within the Wnt/β-catenin pathway and frequently implicated in epithelial-to-mesenchymal transition and tumor progression." (PMID 40941703, 2025). "Furthermore, through experiments utilizing our experimentally generated CAF (exp‐CAF) line and xenograft models, we demonstrated that LEF1 expression in the exp‐CAFs plays a role in promoting tumor growth and is linked to SCC marker‐positive cancer cells." (PMID 39887653, 2025). "LEF1 drives the expression of target genes associated with cellular proliferation, differentiation, and survival, functions that are often hijacked in cancer to promote tumor growth." (PMID 39851951, 2025). "However, our study was limited by insufficient tumor types to demonstrate the diagnostic performance of the combined use of LEF1 and β-catenin in WNT-activated tumors." (PMID 39881334, 2025). "The combined use of LEF1 and β-catenin enhances diagnostic accuracy and may help the identification of these tumor types." (PMID 39881334, 2025).
tumor (continued). "Additionally, we show alterations in interconnected signaling pathways linked to LEF1, causing gene expression changes with broad effects on cell cycle regulation, tumor microenvironment, and implications to cell invasion and metastasis." (PMID 38003292, 2023). "We used conditional alleles of Lef1 in E2a-/- T lymphocytes, that were deleted either before or after leukemic transformation and found that LEF1 can function as either an oncogene or a tumor suppressor depending on the context in which it is deleted." (PMID 35371057, 2022). "Our data demonstrate that the developmental timing of Lef1 mutations impact its apparent oncogenic or tumor suppressive characteristics and demonstrate the utility of mouse models for understanding the cooperation and consequence of mutational order in leukemogenesis." (PMID 35371057, 2022). "We found that Lef1 deletion in Apc-deficient tumor cells was associated with increased nuclear accumulation of β-catenin and up-regulation of its downstream targets Myc and Cd44, which have been considered as key mediators of intestinal tumorigenesis in the Apc-deficient cells." (PMID 34788095, 2021). "To analyze how longer-term Lef1 deletion affects tumor development after a stochastic loss of the remaining WT Apc allele in ApcMin/+ mice, we compared tumor growth in ApcMin/+(ApcMin), Villin-Cre;ApcMin/+;Lef1fl/+(VApcMinLΔ/+), and Villin-Cre;ApcMin/+;Lef1fl/fl (VApcMinL) mice." (PMID 34788095, 2021). "On the other side, it has been demonstrated that TCF1 may act as a tumor suppressor in T-lymphocytes and LEF1 may be deleted and mutated in T-ALL." (PMID 32046053, 2020). "miR-320 overexpression in PCa cells plays a tumor-suppressive role by decreasing PCa tumorigenesis in vitro and in vivo through targeting of lymphoid enhancer-binding factor 1 (LEF1), CD44, SOX9, Oct-4 and CCND1, all associated with the Wnt/β-catenin signaling pathway." (PMID 33426506, 2020). "Based on these results, one may speculate that the inactivation of LEF1 may be causing the prevention of the tumor suppressor effect of DHRS2 in T cells and contributing to leukemogenesis." (PMID 32586085, 2020). "Several downregulated genes were shown to have a strong protein interaction, but most of these genes, such as Fgfr2, Tnc, and Lef1, have been positively associated with tumor progression, suggesting their downregulation is not involved in 4C11+ cells aggressive phenotype." (PMID 31069961, 2019). "Further, the Wnt/β-catenin signaling pathway, which is active in ovarian cancer and tumor progression, may regulate the expression of IDO, a known immunosuppressant, by tumor-associated myeloid cells through an LEF-1-associated mechanism." (PMID 27854240, 2016). "We further analyzed whether reduced tumor vascularization observed in cells expressing the LEF-1-ΔL variant also occurred in tumors of the same size." (PMID 22639890, 2012). "We were unable to test whether LEF1 loss ameliorated tumour development in Ptendel; Fbxw7mut mice." (PMID 37589076, 2023). "Moreover, silencing METTL3 could suppress tumor proliferation and migration and was also associated with lymphoid enhancer-binding factor 1 (LEF1) and Wnt/β-catenin signaling pathway." (PMID 35860263, 2022). "LEF1 is associated with increased Wnt signalling, however, in the current study it appears that genes may be antagonising one another, with genes that both increase and decrease Wnt signalling expressed more highly in tumor compared with non-tumor tissue." (PMID 32854182, 2020). "Remarkably, LEF1 shares with TCF7L1 this stronger link to cell adhesion in tumor tissue, and also an association in normal tissue with muscle, which seems difficult to explain, but could somehow be linked to shared molecular machinery functioning in cell migration." (PMID 32403323, 2020).